ID1 (inhibitor of DNA binding 1)
Diseases named in the same sentence as ID1 in open-access papers (continued):
Sharing a sentence is not in itself a finding about the gene and the disease.
ovarian carcinoma (25 papers, 2005 to 2025). A malignant neoplasm originating from the surface ovarian epithelium. "In ovarian cancer specifically, ID1 expression is associated with poor differentiation, aggressive tumor behavior, and poor clinical outcomes in patients." (PMID 39123206, 2024). "In ovarian cancer, we have observed that some Id1-positive specimens are associated with well-differentiated cancer cells." (PMID 23714001, 2013). "In this study, we investigated the role of Id1 in EPC angiogenesis in patients with ovarian cancer and the underlying signaling pathway." (PMID 23714001, 2013). "Overexpression of ID-1 is associated with more aggressive behavior of tumor cells in ovarian cancer." (PMID 20003244, 2009). "The cell cycle blockade and differentiation caused by such a drug, trichostatin A, caused decreased levels of ID-1 consistent with cell cycle senescence and differentiation of A2780 ovarian cancer cells." (PMID 16001974, 2005). "Here, we investigated whether the ovarian cancer chemoresistance is associated with the autophagy induced by the inhibitor of DNA binding 1 (ID1)." (PMID 32080166, 2020). "Moreover, Maw found that the expression of Id1 was related positively to the clinical stage of ovarian cancer patients, with higher expression associated with more obvious tumor angiogenesis and poorer prognosis." (PMID 25546354, 2014). "We hypothesized that Id1 is linked to the angiogenesis of ovarian cancer EPCs via regulation of the NF-κB/matrix metalloproteinase-2 (MMP-2) and PI3K/Akt pathways." (PMID 23714001, 2013). "Among our ovarian cancer models, ID1 expression was found to be selectively elevated in the CSC-enriched SP which also exhibit increased autophagy." (PMID 39123206, 2024). "Recent studies reported that ID1 conferred ovarian cancer cell chemoresistance through ER stress-mediated induction of autophagy, and RSK2 suppression increased paclitaxel induced apoptosis by regulating autophagy." (PMID 37670384, 2023). "In fact, the level of ID-1 expression correlates with the malignant potential of ovarian cancer, resulting in poor survival outcomes." (PMID 35740568, 2022). "Implication of DNA binding inhibitor proteins in growth and progression of cancer has been confirmed in ovarian cancer, where over expression of inhibitor of DNA binding protein (ID-1) directs the growth of ovarian cancer." (PMID 34234859, 2021). "It has been reported that ID1 knockout in ovarian cancer cells significantly inhibited the growth and invasion of tumor cells and promoted the apoptosis of tumor cells." (PMID 33992097, 2021). "In this report, we have identified that ID1 confers ovarian cancer cell chemoresistance through the ATF6-mediated induction of autophagy, which is a novel discovery in our study." (PMID 32080166, 2020). "In this study, we have identified that ID1 confers ovarian cancer chemoresistance largely through the induction of the IL-6/STAT3/ATF6-mediated autophagy." (PMID 32080166, 2020). "Studies have shown that Id1 is highly expressed in ovarian cancer, thus promoting proliferation and inhibiting apoptosis and differentiation of ovarian cancer cells." (PMID 25546354, 2014). "It has been reported that trichostatin (TSA) effectively inhibits in vitro proliferation and induces anti-differentiation of the sensitive ovarian cancer cell line A2780 via a mechanism that involves downregulation of Id1 protein expression." (PMID 25546354, 2014). "Western blot analysis revealed a higher Id1 expression in human ovarian cancer EPCs than in cells from 20 healthy controls." (PMID 23714001, 2013). "The proliferation, migration, and adhesion properties of ovarian cancer EPCs are attributable to the high expression of Id1, integrin α4 and p-Akt." (PMID 23714001, 2013). "Both Id1 and NF-κB are over-expressed in EPCs from patients with ovarian cancer, which contributes to EPC angiogenesis." (PMID 23714001, 2013).
ovarian carcinoma (continued). "Id1 can enhance EPC angiogenesis in ovarian cancer, which is mainly mediated by the PI3K/Akt and NF-κB/MMP-2 signaling pathways." (PMID 23714001, 2013). "In a previous study, we used real-time RT-PCR to examine mRNA expression of Id1 in EPCs of 25 patients with ovarian cancer." (PMID 23714001, 2013). "In our previous study, we found that EPCs from patients with ovarian cancer transfected with Id1-RNAi-LV displayed less proliferation, migration, and adhesion abilities compared to non-transfected control cells." (PMID 23714001, 2013). "In the present study, we demonstrated that over-expression of Id1 alone can induce angiogenic processes of EPCs in ovarian cancer." (PMID 23714001, 2013). "Id1 and its downstream effectors are potential targets for treatment of ovarian cancer because of their contribution to angiogenesis." (PMID 23714001, 2013). "In ovarian cancer, the level of Id1 protein expression correlates with malignant potential, associated with poor differentiation and aggressive behavior of tumor leading to poor clinical outcome." (PMID 22355333, 2012). "To confirm the role of Id1 in EPCs of patients with ovarian cancer we performed gene-silencing experiments." (PMID 20796276, 2010). "We further explored the effect of Id1 and related signaling pathways on EPCs of patients with ovarian cancer." (PMID 20796276, 2010). "Here, using blood samples from 25 ovarian cancer patients, we demonstrated that Id1 is involved in enhancing EPCs migration and adhesion." (PMID 20796276, 2010). "In various forms of tumours, including ovarian cancer, Id1 and Id3 are overexpressed extensively and in an overlapping pattern." (PMID 20842131, 2010). "Inhibiting Id1 can therefore both disrupt ovarian cancer cells growth and prevent blood vessels from feeding the ovarian cancer cells." (PMID 20796276, 2010). "Ovarian cancer cells ES-2 and PA-1 were treated with different doses of Id1/3-PA7 (1–7.5 μg per 106 cells) at 4 h intervals for 48 h." (PMID 20842131, 2010). "Our real-time RT-PCR analysis indicates that Id1 expression in ovarian cancer is significantly increased compared to that in healthy subjects." (PMID 20796276, 2010). "Next, we evaluated the effects of inhibiting the phosphatidylinositol 3-kinase (PI3K)/Akt signaling pathway on Id1 and integrin α4 in EPCs of patients with ovarian cancer." (PMID 20796276, 2010). "Id1 protein expression in EPCs of 6 patients with ovarian cancer transfected with Id1-RNA-LV was significantly decreased compared to that in control EPCs." (PMID 20796276, 2010). "We knocked down the expression of Id1 by an siRNA-mediated Id1 lentiviral construct to determine the functional importance of Id1 in EPCs of patients with ovarian cancer." (PMID 20796276, 2010). "In this study, we investigated the role of the peptide aptamer Id1/3-PA7 on the progression of cell cycle and apoptosis in Id1- and Id3-overexpressing ovarian cancer cells ES-2 and PA-1." (PMID 20842131, 2010). "Here, we used Id1/3-PA7 to analyse its functional interference in Id1- and Id3-overexpressing ovarian cancer cells ES-2 and PA-1." (PMID 20842131, 2010). "For its delivery into ovarian cancer cells, Id1/3-PA7 was fused with a cell-penetrating protein transduction domain (PTD), expressed and purified from bacteria." (PMID 20842131, 2010). "For its delivery into ovarian cancer cells, Id1/3-PA7 was fused with cell-penetrating PTD, expressed in bacteria and purified under native conditions." (PMID 20842131, 2010). "We used real-time RT-PCR to examine mRNA expression of Id1 in EPCs of 25 patients with ovarian cancer, and Western blot analysis revealed a higher Id1 protein expression in human ovarian cancer EPCs than in 20 healthy controls." (PMID 20796276, 2010). "Id1 and integrin α4 expression were increased in EPCs freshly isolated from ovarian cancer patients compared to those obtained from healthy subjects." (PMID 20796276, 2010).
ovarian carcinoma (continued). "In a previous study, expression of ID-1 was shown as an independent prognostic factor in ovarian cancer with long-time follow-up." (PMID 20003244, 2009). "We demonstrate for the first time that promotion of autophagy by both pharmacological and non-pharmacological strategies leads to proteolytic degradation of ID1 in the CSC-enriched side population (SP) of platinum-resistant epithelial ovarian cancer (EOC) cell lines." (PMID 39123206, 2024). "Importantly, while both ID1-selective and pan-ID family knockdown reduced ovarian cancer stemness properties, ID1-specific depletion elicited more robust effects on critical endpoints." (PMID 39123206, 2024). "Furthermore, ID 1–4 genes were hypomethylated, but E2A was hypermethylated, and in ovarian cancer the expression level of ID-4 mRNA increased while that of E2A mRNA decreased." (PMID 35740568, 2022). "Although ID1 may promote chemoresistance through different pathways in different types of cancer, the clear mechanism is not fully understood in ovarian cancer chemoresistance." (PMID 32080166, 2020). "To determine whether ID1 contributes to ovarian cancer metastasis in vivo, we performed animal assays by intraperitoneal injection of above cells." (PMID 32080166, 2020). "In summary, these data support the rationale of pharmacologic inhibition of the Id1/NF-κB/MMP-2 or Id1/PI3K/Akt pathways for ovarian cancer therapy and suggest that inhibition of Id1 or its downstream molecule MMP-2 removes the protection of ovarian cancer EPC from angiogenesis." (PMID 23714001, 2013). "Moreover, knock-down of Id1 in EPCs almost completely abolished the EPC angiogenic processes in ovarian cancer." (PMID 23714001, 2013). "In the present study, we examined whether the over-expression of Id1 can enhance angiogenesis in cultured human ovarian cancer EPCs." (PMID 23714001, 2013). "After the Id1-RNAi-LV construct was transfected into EPCs of 6 patients with ovarian cancer, integrin α4 mRNA expression levels in transfected cells were compared to those in nontransfected and control-transfected (NC-GFP-LV) EPCs of 6 patients with ovarian cancer by quantitative RT-PCR." (PMID 20796276, 2010). "Ovarian cancer cells ES-2 and PA-1 were treated with Id1/3-PA7 (5 μg per 106 cells)." (PMID 20842131, 2010). "We aimed to determine whether inhibitors of differentiation 1 (Id1) were expressed in circulating EPCs of patients with ovarian cancer, whether Id1 could mediate EPCs mobilization and recruitment, and, if so, what underlying signaling pathway it used." (PMID 20796276, 2010). "The identification of Id1 as a common target gene in EPCs migration and adhesion suggested that Id1 might serve as a novel therapeutic target in ovarian cancer." (PMID 20796276, 2010). "To explain the effect of Id1 on migration toward peripheral blood and recruitment to tumor tissues we explored the expression of integrin α4 on the EPCs surface of 25 patients with ovarian cancer." (PMID 20796276, 2010). "Although not correlated with CCNE1 expression in our analysis, co-amplification of ID1 with CCNE1 may further contribute to cell cycle de-regulation in ovarian cancer." (PMID 21103391, 2010). "Our results indicate that Id1 contributes to the migration and adhesion of EPCs in ovarian cancer patients and that Id1 may be important in the pathogenesis of ovarian cancer." (PMID 20796276, 2010). "Id1 is expressed in bone marrow-derived EPCs and is highly expressed in ovarian cancer cells." (PMID 20796276, 2010). "Taken together, our data support the notion that ovarian cancer EPCs migration and recruitment via the PI3K/Akt-Id1- integrin α4 signaling pathway may be responsible for increased EPCs levels in ovarian cancer." (PMID 20796276, 2010). "In addition, ovarian cancer patients with increased Id-1 levels have shorter survival than those with low Id-1 expression." (PMID 19014499, 2008). "At present, whether ID1 induces autophagy to grant ovarian cancer cell chemoresistance is unknown." (PMID 32080166, 2020).
ovarian carcinoma (continued). "Id1 may mediate EPCs mobilization and recruitment to ovarian cancer tissues." (PMID 20796276, 2010). "In support of this, targeting the ID1/ID3 interaction with the E47 bHLH transcription factor is effective against breast and ovarian cancers." (PMID 35187538, 2021). "The data from TCGA database indicated a positive correlation between ID1 and ATF6 in tissues from ovarian cancer patients treated with platinum." (PMID 32080166, 2020). "In eight ovarian cancer cell lines, low ID1 was detected by western blot in HEY, HEY A8, OVCA420, OVCA433, and A2780 cells, while high expression of ID1 was conceived in SKOV3, SKOV3 ip1, and OVCA429 cells." (PMID 32080166, 2020). "Inhibitor of DNA binding 1 (Id-1), a protein repressed by miR-29b, facilitates the TGFβ1-induced EMT in human ovarian cancer cells." (PMID 30250403, 2018). "Id1 and MMP-2 expression were increased in EPCs freshly isolated from ovarian cancer patients compared to those obtained from healthy subjects." (PMID 23714001, 2013). "We showed that Akt is phosphorylated in EPCs of ovarian cancer patients, and inhibition of PI3K/Akt downregulated the expression level of Id1 and integrin α4 and reduced EPCs functions." (PMID 20796276, 2010). "Peptide aptamer Id1/3-PA7 significantly inhibited proliferation and induced apoptosis in ovarian cancer cells, with deregulated expression of Id1 and Id3." (PMID 20842131, 2010). "The inhibitor of DNA binding 1 (ID1), significantly increased in our platinum-resistant PDOs, has been described to induce autophagy and chemoresistance through the STAT3/ATF6-mediated signalling pathway in ovarian cancer." (PMID 37686015, 2023). "In other types of cancers, such as breast and ovarian cancer, no change in the expression of PGC1α and ID1 was observed between normal tissues and cancer tissues." (PMID 33917757, 2021). "The involved molecules, including ID1, STAT3, and ATF6, may have a potential to be targeted in combination with chemotherapeutic agents to improve ovarian cancer survival." (PMID 32080166, 2020). "Interestingly, activation of NF-κB by Id1 led to the high expression of MMP-2, instead of VEGF, in EPCs from patients with ovarian cancer in the present study." (PMID 23714001, 2013). "Therefore, we investigated the biological effect of the peptide aptamer Id1/3-PA7 in Id1/Id3-overexpressing and CDKN2A-positive ovarian cancer cells, ES-2 and PA-1." (PMID 20842131, 2010). "Id1/3-PA7 could represent an exogenous anti-tumour agent that can significantly trigger cell-cycle arrest and apoptosis in ovarian cancer." (PMID 20842131, 2010). "This could indicate that in PA-1 and ES-2 ovarian cancer cells, Id1/3-PA7 might preferentially inhibit the heterodimerisation of Id1 and Id3 with ETS proteins, which are the positive regulators of CDKN2A." (PMID 20842131, 2010). "Furthermore, we have shown that the biological effects of Id1/3-PA7, in analysed breast and ovarian cancer cells, were counteracted by forced expression of Id1 and Id3." (PMID 20842131, 2010). "ID-1 mRNA levels significantly increased with increasing clinical stages (p < 0.001) of ovarian cancers, regardless of histopathological type." (PMID 20003244, 2009). "To investigate the function of ID1 in ovarian cancer, we first detected the expression level of ID1 in 6 normal ovarian or 21 cancer tissues, and found that no ID1 was detected in all normal tissues and high nuclear ID1 expression was in 15 (71.4%) cancer tissues." (PMID 32080166, 2020). "Cells with high expression of ID1 and ATF6 appeared with higher IC50 values of cispaltin and taxol, indicating that both molecules could be targeted to improve the treatment efficacy of ovarian cancer." (PMID 32080166, 2020). "ID1, STAT3, and ATF6 may be targeted in combination with chemotherapy for ovarian cancer treatment." (PMID 32080166, 2020). "If this is true, Id1-predominant ovarian cancer EPCs may not necessarily be poorly differentiated but surely committed to cellular angiogenesis." (PMID 23714001, 2013).
ovarian carcinoma (continued). "After the Id1-RNAi-LV construct was transfected into EPCs of 6 patients with ovarian cancer, Id1 mRNA expression levels in transfected cells were compared to those in nontransfected and control-transfected (NC-GFP-LV) EPCs of 6 patients with ovarian cancer by quantitative RT-PCR." (PMID 20796276, 2010).